CRP (C-reactive protein)
Diseases named in the same sentence as CRP in open-access papers (continued):
Sharing a sentence is not in itself a finding about the gene and the disease.
COVID-19 (continued). "Heightened serum levels of IL-6, C-reactive protein (CRP) and D-dimer, lymphopenia, neutrophilia, and other complications have been reported in severe COVID-19, associated with the dysregulation of myeloid responses, especially in the lung." (PMID 34064104, 2021). "The main result of this cohort study is that, irrespective of all measured potential confounders including albuminemia, the elevated CRP levels in early COVID-19 were associated with higher 14-day mortality among geriatric patients with COVID-19." (PMID 34506514, 2021). "In terms of laboratory parameters, elevated inflammatory cytokines and infection-related factors, such as TNF-α, IL-6, IL-10, IL-8, IL-1β, IL-2R, ferritin, hs-CRP and procalcitonin were significantly associated with higher death risk of COVID-19." (PMID 34521370, 2021). "These inflammatory markers, such as C-reactive protein (CRP), serum ferritin, and procalcitonin, are associated with disease severity in COVID-19 patients." (PMID 34944639, 2021). "Many past studies reported the association between CRP levels and lung lesions in the severe stage of hospitalized COVID-19 patients." (PMID 34314447, 2021). "Perhaps the greatest challenge has been the association of COVID-19 with elevated C-reactive protein (CRP)." (PMID 34423323, 2021). "To date, data from small studies also suggest a positive association between the level of C-reactive protein and the severity of COVID-19." (PMID 33865314, 2021). "Procalcitonin, urea nitrogen, and CRP were negatively related to COVID-19, as were fever and underlying lung disease." (PMID 33613111, 2021). "A study investigated links between serum inflammatory markers and C-reactive protein (CRP) in COVID-19 patients with cognitive functions and found loss of some domains, such as sustained attention, to be significantly correlated to CRP levels in the blood." (PMID 34362224, 2021). "This indicates an overall increase in COVID-19 biomarkers, such as urea, D-dimer, and creatinine levels in both groups, but a further increase in CRP levels showed a decrease in platelet counts, which was previously associated with COVID-19 severity." (PMID 34150832, 2021). "In the present study, we investigated the diagnostic value of PCT and CRP to detect secondary bacterial infections in patients with COVID-19." (PMID 34021897, 2021). "Most impressively, inflammation markers such as CRP and ferritin showed a high association with poor outcome in all groups, but most pronounced in COVID-19, which confirms and corroborates results from earlier studies." (PMID 34204453, 2021). "Blood ferritin, together with other biomarkers such as C-reactive protein or D-dimer have been proposed to be used in risk stratification to predict severe and fatal COVID-19 in hospitalized patients." (PMID 35010300, 2021). "In solid-organ transplant recipients with COVID-19, initial CRP and N/L ratio were associated with need for mechanical ventilation." (PMID 33034239, 2021). "A recent meta-analysis of 32 studies and >10,000 COVID-19 patients found that CRP was independently associated with higher risk of composite severe COVID-19 outcome (pooled-OR: 4.37; 95% CI 3.37–5.68)." (PMID 34567235, 2021). "Comparison of laboratory tests between patients who died from COVID-19 and those who recovered suggested that CRP and procalcitonin levels were associated with mortality." (PMID 34061779, 2021). "The finding that higher CRP levels are associated with higher mortality risk in older patients with COVID-19 has interesting potential clinical and research implications." (PMID 34506514, 2021). "Results of the current study revealed a positive association between CRP level and lung disorders in COVID-19 patients." (PMID 33861750, 2021). "Progressive respiratory illness in COVID-19 is associated with marked elevation of inflammatory markers such as CRP, PCT, ferritin and D-dimer." (PMID 33709775, 2021).
COVID-19 (continued). "Elevated CRP levels were associated with poorer 14-day survival in hospitalized geriatric COVID-19 patients." (PMID 34506514, 2021). "Cytokine storm causing lymphopenia, leukopenia, and high CRP levels were associated with COVID-19 severity." (PMID 33446135, 2021). "We next examined if plasma protease inhibitor concentrations correlated with CRP because this clinical biomarker associates with active inflammation and severity of COVID-19." (PMID 34458849, 2021). "Of the commonly measured laboratory parameters included in the predictive models, sodium, CRP, glucose and leucocytes were positively correlated with severe COVID-19, indicating that higher values pose a higher risk for worse outcomes." (PMID 33546711, 2021). "Worsening of the virus infection, from the onset of symptoms to the development of ARDS, has been reported to be associated with a concomitant increase in CRP, and CRP has prognostic value in patients severely affected by COVID-19." (PMID 35011944, 2021). "Elevated pro-inflammatory cytokines such as interleukin-6 (IL-6) and C-reactive protein (CRP) have been seen in patients with Coronavirus Disease 2019 (COVID-19) and are associated with worse outcomes." (PMID 33510335, 2021). "In this study, we screened eight severity-associated clinical markers of lactate dehydrogenase, C-reactive protein, albumin, comorbidity, electrolyte disturbance, coagulation function, eosinophil and lymphocyte counts in COVID-19 patients." (PMID 34372792, 2021). "Systemic inflammation as measured by C-reactive Protein is strongly associated with severity and mortality in COVID-19." (PMID 34867791, 2021). "They found that high CRP (OR = 1.16, p = 0.033) and low albumin (OR = 0.91, p = 0.030) were risk factors for poor prognosis in patients with diabetes and COVID-19." (PMID 34164413, 2021). "It was reported that reduced levels of HDL in COVID-19 patients were associated with increased levels of the inflammatory marker C-reactive protein (CRP) and possibly development of the “cytokine storm” that was observed in certain COVID-19 patients." (PMID 34638523, 2021). "Of note, recent reports indicated that COVID-19 patients presented elevated CRP contents, and high levels of CRP were closely associated with more severe forms of COVID-19, where age was considered the main risk factor for poor outcome." (PMID 34447386, 2021). "COVID-19 causes neutrophilia, lymphopenia, leukopenia, thrombopenia, and anemia as well as increased expression of systemic inflammatory proteins IL-6, C-reactive protein (CRP), innate chemokines (CXCL10, CCL2, CCL3) and the proinflammatory cytokine TNF-α." (PMID 33346851, 2021). "Decreased serum albumin levels (<3.5 g/dL) were found more frequently in COVID-19 patients with thromboembolic events compared to thrombosis-free patients, usually in association with elevated levels of C-reactive protein and D-dimer." (PMID 34441957, 2021). "The association between both low and high serum LDL-C level (U-shaped) and high risk of severe COVID-19 was present after adjusting for age, gender, underlying disease, CRP, LDH, NLR, HDL-C, BMI, and hypolipidemic drugs." (PMID 34504873, 2021). "The multivariable logistic regression analysis indicated that COVID-19 patients with increasing age (P = 0.035), higher levels of CRP (P = 0.038), and TNI (P = 0.036) were associated with increased death than other patients." (PMID 34725560, 2021). "Elevated LDH and CRP, as well as decreased oxygenation index and lymphocyte count were reported to be associated with severe disease progression in patients with COVID-19." (PMID 33815147, 2021). "Previous studies have shown an association between CRP and D-dimer levels and myocardial injury in COVID-19." (PMID 34928467, 2021). "Our study identified age, sex, CKD, baseline CRP, and respiratory involvement as factors associated with hospital mortality in COVID-19 patients admitted to a large academic hospital in London, UK." (PMID 33564474, 2021).
COVID-19 (continued). "Inflammatory biomarkers, such as C-reactive protein, ferritin, and procalcitonin, have been associated with mortality among COVID-19 patients." (PMID 34122677, 2021). "In another study, maximal IL-6 (>80 pg/mL) and CRP (>97 mg/L) levels before intubation showed the strongest association with the need for mechanical ventilation in a cohort of COVID-19 hospitalized patients." (PMID 33815405, 2021). "Higher serum levels of inflammatory marker, CRP, was identified as risk factors of sudden death with COVID-19 patients." (PMID 33828847, 2021). "Being critically ill and lymphocyte count, SOFA score, APACHE II score, PaO2/FiO2, IL-6, and CRP on admission were associated with poor prognosis in COVID-19 patients." (PMID 34167463, 2021). "A previous study of COVID-19 survivors indicates a relationship between cognitive dysfunction in maintaining attention and underlying inflammation as measured by CRP." (PMID 34685427, 2021). "CRP and albumin, which are acute phase reactants, are associated with severe COVID-19, a highly inflammatory state." (PMID 34123422, 2021). "Overall haematological and biochemical findings that have been associated with COVID-19 including raised CRP, d-dimer and ferritin were similarly distributed between the two cohorts." (PMID 33510247, 2021). "Higher-risk subgroups of COVID-19 patients tend to have lymphopenia accompanied by overall leucocytosis and high levels of inflammatory markers (C-reactive protein [CRP], fibrinogen, ferritin, IL-6)." (PMID 33832474, 2021). "Although several authors have found an association between CRP, lymphopenia, severity, and mortality in COVID-19, few have evaluated the CLR in this context." (PMID 34945746, 2021). "In line with this, patients from our study showed high levels of C-reactive protein and ferritin, other parameters that have been associated with the inflammatory cytokine storm related to COVID-19." (PMID 33917093, 2021). "According to univariate logistic regression analysis, 24 variables, including age, comorbidities, fever, and ln (CRP), were associated with the severity of COVID-19 and included in the multivariate logistic regression analysis (forward likelihood method)." (PMID 33681245, 2021). "Elevated IL-6 and C-reactive protein (CRP) were observed in deceased patients with COVID-19, suggesting that SARS-CoV2 causes a “cytokine storm syndrome”." (PMID 32864934, 2020). "We then studied the correlation between TL (expressed in percentile) and biological factors previously associated with poorer COVID-19 outcome, namely C-reactive protein level (CRP), lymphocyte count, NLR and eosinophils." (PMID 33104521, 2020). "Accordingly, in an observational study on hospitalized COVID-19 cases, early use of glucocorticoids was effective only in patients with high CRP levels, being instead associated with increased mortality in case of low CRP." (PMID 33123149, 2020). "Our automated workflow identified C-reactive protein (CRP) as one of the COVID-19–associated genes with “medium” confidence." (PMID 33055059, 2020). "• COVID-19 patients showed increased levels of serum CRP, which was associated with disease progression.• CRP levels were suggested as a predictive marker in early stage COVID-19." (PMID 33335518, 2020). "The results of both analyses showed that comorbidity, ALB, CRP, and age ≥60 years were the most influential risk factors for severe COVID-19 in these patients." (PMID 33330318, 2020). "The risk of developing severe COVID-19 in patients with a serum CRP of ≥65.08 mg/L is 8.9 times than in patients with a serum CRP≤65.08 mg/L." (PMID 32589691, 2020). "A study undertaken in Wuhan, China, that evaluated the clinical characteristics of COVID-19 patients also found an important association of CRP with severe disease prognosis." (PMID 32913691, 2020). "In previous studies, high levels of Fibrin-D-dimer and C-reactive protein (CRP) have been associated with poor outcome in COVID-19." (PMID 33225952, 2020).
COVID-19 (continued). "Patients who are at least 63 years old, with an absolute lymphocyte value less than 1.02×10^9/L, and a CRP greater than 65.08 mg/L are at greater risk of developing severe COVID-19 with corresponding odds ratios of 41.0, 6.1, and 8.9, respectively." (PMID 32589691, 2020). "Elevated CRP was associated with mortality in an adult COVID-19 cohort from China and need for MV in a pediatric COVID-19 cohort." (PMID 33340348, 2020). "Meanwhile, the presence of diabetes was positively associated with hs-CRP and IL-6 in the COVID-19 patients." (PMID 33062712, 2020). "Nutritional risk was associated with severe COVID-19 (p < 0.01; p < 0.01 after adjustment for C reactive protein), as were lower plasma proteins, albumin, prealbumin, and zinc levels (p < 0.01)." (PMID 33260603, 2020). "The univariate logistic regression analysis showed that the age, comorbidity, hypertension, lymphocyte count, neutrophil count, NLR, albumin and CRP were associated with the disease severity of COVID-19." (PMID 33110593, 2020). "Subsequent observational retrospective series of critically ill Chinese COVID-19 patients treated with tocilizumab also reported a decrease in CRP levels, mechanical ventilation risk and mortality rate." (PMID 33442386, 2020). "The previously reported modifications in severe forms of COVID-19 showed increased levels of C-reactive Protein [CRP], ferritin, lactate dehydrogenase [LDH]), associated with a marked lymphopenia of CD4 and CD8 T-cell subsets." (PMID 33178207, 2020). "In univariate logistic analysis, male sex, fever, increased CRP, and pneumonia on chest radiograph were reported as factors associated with the prognosis of elderly patients with COVID-19, which is similar to previous studies." (PMID 33291617, 2020). "Considering that CRP was one of the most reported risk factors of the disease severity of COVID-19 patients, ROC curve was conducted to determine the predictive performances of FT3 and CRP in the disease severity." (PMID 33117282, 2020). "COVID-19 is, in general, associated with heightened cytokine release, as indicated by elevated blood levels of IL-6 and C-reactive protein (CRP)." (PMID 32668803, 2020). "In fact, preliminary data from more than 5,000 patients with COVID-19 suggested a relationship between vitamin D deficiency and severity of cytokine storm, indicated by high serum levels of the inflammatory marker C-reactive protein (CRP)." (PMID 33365326, 2020). "Particularly, a CRP level greater than 10 mg/L suggested a higher risk for ICU admission in COVID-19 patients with CVD." (PMID 32765943, 2020). "An article describing the risk factors associated with hepatic injury in COVID-19 patients suggested the presence of lymphopenia and high CRP level to be independent risk factors for liver enzymes abnormalities." (PMID 33365223, 2020). "Severe respiratory disease caused by COVID-19 is characterized by severe hypoxia and elevated serum levels of acute phase reactants including ferritin, C-reactive protein (CRP) and lactate dehydrogenase (LDH)." (PMID 32546029, 2020). "Thrombocytopenia with elevated D-dimer and C-reactive protein in severe COVID-19 and stroke are consistent with a virus-associated microangiopathic process." (PMID 33329335, 2020). "In accordance with Liu J’s and Wan S’s study, this study also found that the levels of lymphocyte count, neutrophil count and CRP were associated with the severity of COVID-19." (PMID 32677918, 2020). "The purpose of this article was to offer an insight into the potential use of C-reactive protein (CRP) levels as a diagnostic index of disease severity and a guide for therapeutic options in COVID-19–infected patients." (PMID 32588812, 2020). "This study indicates that patients with elevated concentrations of serum CRP on admission are at an increased risk of experiencing severe COVID-19." (PMID 32589691, 2020).
COVID-19 (continued). "Increases in C-reactive protein (CRP) are used to track the inflammatory process of COVID-19 and are associated with disease state progression." (PMID 33206183, 2020). "Elevations in CRP (C-reactive protein), strongly associated to interleukin (IL)-6 levels, appear to be unique to COVID-19 patients when compared to other viral infections." (PMID 33335532, 2020). "Increased IL-6 is a hallmark of COVID-19 patients along with high levels of C reactive protein, therefore using Tocilizumab has been recommended after effective results in treating such patients to manage cytokine release syndrome (CRS)." (PMID 32781571, 2020). "The COVID-19 is inclined to cause a decrease of lymphocyte count and an increase of C reactive protein (CRP), especially in severely ill patients." (PMID 32754163, 2020). "Our results also showed that thyroid dysfunction was associated with increased inflammation biomarkers including CRP and leucocytes, indicating inflammatory reaction played an important role in thyroid dysfunction of COVID-19." (PMID 33679608, 2020). "In conclusion, we determined that older age, a respiratory rate over 24 breaths per minute, and elevated TnI and CRP levels are risk factors for ICU admission in COVID-19 patients with CVD." (PMID 32765943, 2020). "Analytical variables such as C-reactive protein, lymphopenia, and anemia indicate the association between the degree of inflammation and the risk for severe COVID-19." (PMID 32977606, 2020). "Hypoalbuminemia and elevated CRP has been shown to be associated with severe illness and death in patients with COVID-19." (PMID 33224959, 2020). "To find the possible reason of the hypercoagulability in cancer patients with COVID-19, we analyzed the association of coagulation indexes and platelet parameters with the levels of CRP, PCT, IL-6, lymphocytes and PaO2." (PMID 32766161, 2020). "The association between high concentrations of CRP and COVID-19 severe clinical presentations has also been reported in several other studies." (PMID 33297986, 2020). "In our study, increased CRP levels measured at admission of patients with COVID-19 was associated with increased mortality risk." (PMID 32867787, 2020). "Several studies have identified an increased risk of mortality in COVID-19 patients with elevated CRP." (PMID 33186355, 2020). "In the end, the mechanism by which pro-inflammatory neutrophils and CRP aggravate the disease of COVID-19 and cause poor prognosis remains to be further investigated." (PMID 33192519, 2020). "More than 25 papers (from the CORD-19 data set) related to the association between CRP and COVID-19 were identified through our computational workflow." (PMID 33055059, 2020). "In fact, Luo and colleagues reported that TCZ administration stabilizes clinical outcomes with a reduction of increased C-reactive protein levels in more than half of COVID-19 patients at risk of a cytokine storm." (PMID 33014208, 2020). "According to Lu J’s study, a simple mortality risk index, composed of age and CRP, can predict COVID-19 related short-term mortality." (PMID 32677918, 2020). "Need for mechanical ventilation in children with COVID-19 has been associated with elevated CRP in one single-center study." (PMID 33340348, 2020). "In this retrospective cohort study originating in NYC, older age, admission levels of D-dimer of more than 1000 ng/mL, CRP of more than 200 mg/L and lymphopenia were associated with mortality in individuals hospitalized for COVID-19." (PMID 32726241, 2020). "Following adjustment in the multivariate model, only CRP > 82 mg/L on admission remained significantly associated with mortality from COVID-19 (ORadj 2.01, 95% CI 1.03–3.91, p = 0.040)." (PMID 33322317, 2020). "The clinical course of severe COVID-19 patients is the rapid deterioration of respiratory function associated with rising markers of systemic inflammation (CRP and ferritin)." (PMID 32699149, 2020).